CDC20 (cell division cycle 20)
Diseases named in the same sentence as CDC20 in open-access papers (continued):
Sharing a sentence is not in itself a finding about the gene and the disease.
breast cancer (continued). "With the exception of UQCRH and LRP8, the expression levels of genes positively correlated with YBX1, such as CTPS1, FMNL2, CDC20, B3GNT5, MTHFD1L, and CDCA8, were significantly and positively correlated with the expression level of YBX1 in 13 breast cancer cell lines." (PMID 30647855, 2018). "Breast cancers and breast cancer cell lines overexpress several mitotic regulators, including kinases that regulate the SAC such as Nek2, Mad1L1, Mad2L1, Mad2L2, BubR1, BubR1B, Bub3, Cdc20, and Mps1/TTK." (PMID 29100415, 2017). "The identified DEGs, which were involved in cell cycle, including CDC20, BUB1, GLIPR1, MCM2, and CCNB1, could have a crucial function in the development of breast cancer, and may become potential targets or prognostic markers for breast cancer." (PMID 25385471, 2015). "Similarly, previous studies had stated that ASPM, CDC20, BUB1B, and CDCA8 expression could be potential poor survival prognostic biomarkers in lung adenocarcinoma, prostate/breast cancer, glioblastoma, respectively." (PMID 36186000, 2022). "However, studies on role of CDC20 in breast cancer are seldom reported till now, most of which are not systematic and conclusive." (PMID 32285914, 2020). "Moreover, CDC20 was significantly reduced in non-triple-negative and non-basal-like breast cancer patients compared with triple-negative and basal-like breast cancer patients." (PMID 32285914, 2020). "CDC20, CDK1, and PLK1 may be the targets of podophyllotoxin in breast cancer." (PMID 32848800, 2020). "Interestingly, a converse relationship of Cdc20 and SMAR1 was observed in breast cancer patient samples, with under expression of SMAR1 in higher grades supporting that oncogenic Cdc20 limits SMAR1 levels in higher grade of breast cancer." (PMID 28617439, 2017). "Interestingly, Cdc20-mediated degradation of SMAR1 promotes cell migration and invasion.The reciprocal relationship of the duo is evident in breast cancer cell lines as well as in patient samples, suggesting that Cdc20 functions as an important negative regulator of SMAR1 in higher grades of cancer." (PMID 28617439, 2017). "Indeed, the overexpression of CDC20 was demonstrated in breast cancer cell lines and primary breast tumors but not in normal mammary epithelial cells or breast tissues." (PMID 22479587, 2012). "However, unlike Cdh1, depletion of Cdc20 failed to induce p-Y419-Src in breast cancer cells." (PMID 31420536, 2019). "Immunoprecipitation showed that SETDB2 endogenously interacted with BUBR1 rather than MPS1, CDC20, or MAD2 in MCF7, MDA‐MB‐231, and SUM159PT breast cancer cells." (PMID 38151757, 2024). "However, five genes (CDC20, MET, KIF23, ANXA1, and CASP1) that are found in the TNBC group were not highly expressed in the HR+ breast cancer subtypes but are commonly found in the ER−/PR+ and ER−/PR− groups such that they could be used as negative controls." (PMID 39000600, 2024).
lung cancer (47 papers, 2012 to 2025). A malignant neoplasm involving the lung. "Loss of CDC20 suppressed the growth and migration of lung cancer cells by inhibiting the MAPK signaling pathway and induced cell cycle arrest." (PMID 39114311, 2024). "These associations include APC/CDC20 for EML4-ALK fusions in lung cancers, SPOP for NUP98-NSD1 and BCR-ABL fusions in LAML, and FBW7 (or FBXW7, F-box and WD repeat domain containing 7) for CCDC6-RET fusions in thyroid carcinomas (THCAs)." (PMID 34795215, 2021). "Notably, silencing of CDC20 caused cell cycle arrest at the G2/M phase and diminished the colony-forming ability of lung cancer cells." (PMID 39795587, 2024). "We provide evidence that either loss of Cdc20 expression or inhibition of APC/C activity promotes senescence in normal human lung fibroblasts while it causes apoptosis in non–small cell lung cancer (NSCLC) cells through a mechanism that requires loss of securin expression." (PMID 35988650, 2022). "Nowadays, CDC20 is widely believed to be associated with a poor lung cancer prognosis." (PMID 35859798, 2022). "CDC20 has been observed as expressed higher in different kinds of human cancers and was associated with poor prognosis such as, oral squamous cell carcinoma, gastric cancer, urothelial bladder cancer, colorectal cancer, lung cancer, and pancreatic cancer." (PMID 32285914, 2020). "CDC20 expression is upregulated in several types of cancer, including lung cancer, liver cancer, prostate cancer and brain cancer." (PMID 40439120, 2025). "Its CDC20 is upregulated in several types of cancer, such as lung cancer, liver cancer and prostate cancer." (PMID 40439120, 2025). "Tissue chip immunohistochemistry further confirmed that the CDC20 protein expression level in lung cancer was significantly greater than that in normal lung tissue (P < 0.05)." (PMID 39895786, 2025). "Targeting CDC20 is increasingly considered as a potential therapeutic strategy in several cancers including lung cancer." (PMID 38419324, 2024). "For H1975 cells, the numbers were 110, 39, 48, and 58.The results from the Wound healing assay and Transwell migration assay demonstrated a significant inhibition of migratory and invasive abilities in lung cancer cells upon CDC20 knockdown." (PMID 39114311, 2024). "Immunofluorescence results indicate that CDC20 is highly expressed in mouse lung cancer and its knockdown significantly reduces tumor size, indicating its involvement in tumor formation in vivo." (PMID 39114311, 2024). "We found that the protein and mRNA expression levels of CDC20 were significantly higher in all three lung cancer cells compared to the normal epithelial cells, with H1299 and H1975 cells showing relatively higher expression." (PMID 39114311, 2024). "Compared to normal lung tissue, the expression of CDC20 in mouse lung cancer tissues was significantly increased." (PMID 39114311, 2024). "Three DEGs shared the common pathways like CDKN20 in non‐small cell lung cancer and viral carcinogenesis, CDC20 in ubiquitin mediated proteolysis and viral carcinogenesis and PPP2R2A in Adrenergic signalling in cardiomycytes." (PMID 39434198, 2024). "In conclusion, the results obtained in vivo validate the role of CDC20 downregulation in tumor initiation and progression in lung cancer." (PMID 39114311, 2024). "BUB3 directly binds to LNC CRYBG3 and interrupts its interaction with CDC20 to result in aneuploidy, thus promoting the tumorigenesis and metastasis of lung cancer cells." (PMID 36787437, 2023). "We analyzed lung cancer cohorts with KRAS mutations (GSE31210) and found that higher hub gene levels (BUB1, BUB1B, NCAPG, CDC20, CDK1, KIF11) were significantly associated with worse OS in lung cancer patients with KRAS mutations." (PMID 36176446, 2022). "Patients with lung cancer who test positive for CDC20 had a shorter OS and RFS, particularly those with NSCLC." (PMID 35859798, 2022).
lung cancer (continued). "Recent studies have shown that CDC20 promotes several types of cancer progression, including glioma and lung cancer." (PMID 36176446, 2022). "In this study, we found that the expression of BUB1, CCNA2, CDC20 and KIF11 increased after inhibitor resistance compared with inhibitor-sensitive lung cancer samples, and these targets were associate with cell cycle, cell proliferation, DNA damage and EMT." (PMID 36176446, 2022). "Studies have shown that the high expression of CDC20 is closely related to the clinical progress of human malignant tumors, such as lung cancer, liver cancer, malignant glioma, etc." (PMID 34696748, 2021). "CDC20 is highly overexpressed in NSCLC patients, and downregulation of CDC20 expression can slow down the growth and colony formation rate of lung cancer cells." (PMID 34712733, 2021). "Although several studies have assessed the role of CDC20 for the initiation and progression of several human cancers including colorectal cancer, lung cancer, glioma, and ATL, few have studied the role of CDC20 in DLBCL." (PMID 30393234, 2019). "Indeed, overexpressed CDC20 at both the genes and protein levels have been previously reported in many cancers, including BC, pancreatic, prostate, colorectal, bladder, and lung cancer." (PMID 39061186, 2024). "After knocking down CDC20, the tumor volume and weight were significantly reduced, suggesting that CDC20 may affect the progression of lung cancer in mice." (PMID 39114311, 2024). "Simultaneously, we aim to validate the significant impact of CDC20 on lung cancer in vivo." (PMID 39114311, 2024). "We find that downregulation of Cdc20 in non–small cell lung cancer (NSCLC) cells is sufficient to inhibit cell proliferation and growth in soft agar and to promote apoptosis, but not senescence, in a manner dependent on downregulation of securin following GSK-3β-mediated securin phosphorylation." (PMID 35988650, 2022). "Furthermore, AURKB, CCNB2, CDC20, CDCA5, CDCA8, CENPF, and KNTC1 are were highly expressed in lung cancer tissues and were associated with poor prognosis." (PMID 35598017, 2022). "Moreover, knockdown of CDC20 gene inhibited cell growth and induced the G2/M arrest in cell cycle of lung cancer cells." (PMID 33777535, 2021). "CDC20 together with CENPA, CDK1, AURKA, and TPX2 were also diagnostic biomarkers in LUAD, and elevated mRNA levels of CDC20 were correlated with poor prognosis of lung cancer." (PMID 34650921, 2021). "EPIC1 downregulation decrease the expression of Cyclin A1, Cdc20, and Cdc45 in lung cancer cells." (PMID 32322669, 2020). "Subsequent studies have indicated that the inhibition of CDC20 expression could reduce the colony formation rate of lung cancer cells in NSCLC and SCLC." (PMID 33186389, 2020). "Therefore, we selected the LA-4 mouse lung cancer cell line to investigate whether knocking down CDC20 would inhibit the growth of mouse lung tumors." (PMID 39114311, 2024). "In parallel, in the lung, Bcl-2/Bax and lung cancer-related factors CDK1, CDC20, P38α etc were significantly increased in stress+smoke group." (PMID 36417428, 2022). "The CDC6, CDC20, and CHEK1 genes are closely related to the occurrence and development of small-cell lung cancer, and CHEK1 is treated as a therapeutic target for lung cancer." (PMID 35632527, 2022). "Compared to primary lung cancer, all the expression of hub genes increased in lymph node metastasis samples, and the expression of BUB1, BUB1B, CDK1, CCNA2 and CDC20 were related to peritoneum metastasis." (PMID 36176446, 2022). "A signature of genes including CDC20, CCNB1, CDC2, CDKN3, MAD2L1, PRC1 and RRM2, were prognostic for 5-year survival in over 400 lung cancer cases, and interestingly, CDC20, CDC2, CCNB1 were also highly overexpressed in the aggressive case." (PMID 22905093, 2012).
lung cancer (continued). "We therefore conclude that BARX1 transactivates CDC20, CDC45, TRIM37 and MMP-9 genes, thereby promoting cellular proliferation, migration and invasion of lung cancer cells due to the functional roles of these genes in cell-cycle progression, DNA synthesis and their association with carcinogenesis." (PMID 37587140, 2023). "In addition, the expression level of main hub genes (BUB1, CCNA2, CDC20, KIF11) was significantly higher in patients with EGFR TKI-resistant lung cancer tissues (GSE161584) than EGFR TKI-sensitive lung cancer tissues." (PMID 36176446, 2022). "Furthermore, this study found that the expression of other lung cancer-related factors CDK1, CDC20, P38α and CUEDC were all significantly increased in the left lung of stress+smoke mice when compared to the each single group." (PMID 36417428, 2022). "Immunoblotting showed that Cdc20 was highly expressed in 786-O, A498, and ACHN among cell lines in kidney cancer, and in PC3 of 4 prostate cancer cell lines, and NCI-H1299 and PC-9 of 6 lung cancer cell lines." (PMID 34527589, 2021). "In addition, a previous study reported that CCNA2, CDC20, PBK, and TOP2A that interacted with CDK1 play vital roles in survival outcomes in human lung cancer." (PMID 32426332, 2020). "Together, our findings provide evidence that Cdc20/APC/C/securin-dependent signaling is a key regulator of cell survival, and its disruption promotes premature senescence in normal lung cells and induces apoptosis in lung cancer cells that have bypassed the senescence barrier." (PMID 35988650, 2022). "Considering the functional characteristics of CDC20, CDC45, TRIM37 and MMP9, it is not surprising that BARX1 promotes cellular proliferation, migration and invasion of lung cancer cells by transactivating CDC20, CDC45, TRIM37 and MMP-9 expression." (PMID 37587140, 2023).
prostate carcinoma (44 papers, 2012 to 2026). A carcinoma that arises from epithelial cells of the prostate gland. "In keeping with that, the association between CDC20 mRNA expression and the Gleason scores was also significant based on prostate cancer datasets in Oncopression." (PMID 37528490, 2023). "A positive correlation between KMT5A and CDC20 expression was also observed in clinical prostate cancer samples, further supporting this association." (PMID 37509260, 2023). "Previous findings indicated that the oncogenic CDC20 was overexpressed in prostate cancer, partially caused by the frequent mutation of Speckle-type POZ (pox virus and zinc finger protein) protein." (PMID 37528490, 2023). "High CDC20 expression was associated with advanced tumor stage in breast, colon, endometrium, and prostate cancer and HCC." (PMID 32596342, 2020). "A study investigating the relationship between CDC20 gene expression and tumor grade and stage in various cancers found a significant association between high CDC20 expression and advanced stages in breast, colon, endometrial, and prostate cancers." (PMID 39795587, 2024). "Furthermore, CDC20 expression is associated with resistance to docetaxel and is implicated in the wnt/Beta-catenin pathway which is oncogenic in advanced prostate cancer." (PMID 37509260, 2023). "Notably, high expression of CDC20 has been reported to be tightly associated with advanced clinical stages and poor prognosis in human cancers, such as prostate cancer." (PMID 34527589, 2021). "Through integrative studies, including CRISPR-Cas9i screening across various prostate cancer cell models, analysis of clinical cancer-specific expression, relevance to patient prognosis, and in vitro loss-of-function validation, we identified three cancer-specific targets: CDC20, RRM2, and DTL." (PMID 41492471, 2026). "To further confirm the role of CDRs in prostate cancer cell growth, we ablated the endogenous expression of CDC20, RRM2, and DTL with cutting-edge RNA-targeted CRISPR-Cas13." (PMID 41492471, 2026). "While previous studies have highlighted the oncogenic roles of CDC20 and RRM2 in prostate cancer, our work further demonstrates that DTL plays a comparable tumor-driving role in prostate cancer compared with CDC20 and RRM2." (PMID 41492471, 2026). "Research on prostate cancer has demonstrated that the depletion of CDC20 can enhance CD8 T lymphocyte infiltration in a GSDME-dependent manner, thereby amplifying antitumor immunity." (PMID 40181976, 2025). "This has been supported by a study that found that CDC20 is important to the function of prostate cancer stem-like cells—cells that are involved in cancer spreading and relapse." (PMID 40227503, 2025). "High expression of Cdc20 is strongly correlated with advanced clinical stages and poor prognosis in various human cancers, including prostate cancer." (PMID 40771930, 2025). "Prior research has indicated that CDC20 downregulation can bolster an anti-tumor immune response of prostate cancer by facilitating CD8 lymphocyte infiltration dependent on GSDME." (PMID 40688701, 2025). "According to reports, silencing of CDC20 inhibits the growth of prostate cancer and enhances sensitivity to docetaxel chemotherapy." (PMID 39114311, 2024). "In prostate cancer, CDC20 has been reported to function as an independent predictor for biochemical recurrence." (PMID 38612439, 2024). "Taken together, this suggests that the positive correlation between KMT5A and CDC20 observed in our cell line models is also observed in advanced prostate cancer." (PMID 37509260, 2023). "A recent study revealed that CDC20 exerted an inhibitory effect on antitumor immune responses and facilitated prostate cancer pathogenesis." (PMID 38283351, 2023). "CDC20 has been proposed to exhibit an oncogenic role in a number of cancers including prostate cancer." (PMID 37509260, 2023).